GP1BB (glycoprotein Ib platelet subunit beta)
Description:
Gp-Ib, a surface membrane protein of platelets, participates in the formation of platelet plugs by binding to von Willebrand factor, which is already bound to the subendothelium.
Synonyms: GP-Ib beta; GPIbB; CD42c; GPIbbeta; BDPLT1; BS
Tractability: Small molecule: a structure with a bound ligand is known. Antibody: its Gene Ontology location is reachable by antibodies, with high confidence; UniProt predicts a signal peptide or a membrane-spanning region.
Gene: Protein-coding gene on chromosome 22 (19,723,539 to 19,724,776, forward strand). Ensembl gene ENSG00000203618.
Subcellular location: Membrane
Pathways (Reactome):
Hemostasis: Amplification and propagation of coagulation cascade; FXIIa, PKa-dependent activation of coagulation pathway; GP1b-IX-V activation signalling; Platelet Adhesion to exposed collagen; Platelet Aggregation (Plug Formation); Regulation of clotting cascade
Disease: Defective F9 activation; Defective binding of VWF variant to GPIb:IX:V; Enhanced binding of GP1BA variant to VWF multimer:collagen
Gene Ontology:
Molecular function: identical protein binding; protein binding; transmembrane signaling receptor activity
Biological process: blood coagulation, intrinsic pathway; positive regulation of platelet activation; release of sequestered calcium ion into cytosol; cell surface receptor signaling pathway; megakaryocyte development; platelet activation; blood coagulation
Cellular component: glycoprotein Ib-IX-V complex; plasma membrane; membrane
Genetic constraint (gnomAD): Loss-of-function variants: 4 observed, 2.85 expected, observed/expected ratio (o/e) 1.4, 90% interval 0.62 to 1.92. That is too few expected variants to judge how well the gene tolerates losing a copy. Missense variants: 302 observed, 189.41 expected, observed/expected ratio (o/e) 1.59, 90% interval 1.45 to 1.75. Synonymous variants: 184 observed, 112.17 expected, observed/expected ratio (o/e) 1.64, 90% interval 1.45 to 1.85.
Gene-disease validity (ClinGen):
ClinGen rates the evidence that GP1BB causes each of these diseases.
Bernard-Soulier syndrome (autosomal recessive): Definitive. Bernard Soulier syndrome (BSS) is an inherited platelet disorder characterized by mild to severe bleeding tendency, macrothrombocytopenia and absent ristocetin-induced platelet agglutination.
Homologues: Orthologues: chimpanzee GP1BB (99% identical), macaque GP1BB (96% identical), mouse Gp1bb (87% identical), pig GP1BB (83% identical), guinea pig GP1BB (76% identical), zebrafish gp1bb (41% identical), tropical clawed frog gp1bb (36% identical). Paralogues in human: GP9 (28% identical).
Diseases named in the same sentence as GP1BB in open-access papers:
GP1BB is named in the same sentence as 24 diseases in open-access papers, as found by Europe PMC text mining. Sharing a sentence is not in itself a finding about the gene and the disease. The quoted sentences say what the papers report.
Bernard-Soulier syndrome (9 papers, 2013 to 2024). "Mutations of GP1BB are associated with Bernard-Soulier syndrome, an extremely rare inherited bleeding disorder." (PMID 28814981, 2017). "Deletion or reduced expression of Gp1bb is associated with a human bleeding disorder, Bernard-Soulier syndrome." (PMID 24131868, 2013). "The first is the bleeding disorder Bernard-Soulier syndrome, which is caused by homozygous or compound heterozygous mutations of the GP1BB gene encoding the platelet glycoprotein GPIb/IX receptor." (PMID 23704059, 2013). "Interestingly, mice with Bernard-Soulier-syndrome (BBS) caused by genetic deletion of the platelet glycoprotein (GP) Ibβ (GP1BB) demonstrated increased levels of SEPT5 in the megakaryocytic linage." (PMID 28224124, 2017). "Bernard-Soulier syndrome (BSS) is an autosomal-recessive bleeding disorder caused by biallelic variants in the GP1BA, GP1BB, and GP9 genes encoding the subunits GPIbα, GPIbβ, and GPIX of the GPIb-IX complex." (PMID 34638529, 2021). "GP1BB (MIM: 138720) has traditionally been linked to a recessive bleeding and platelet disorder called Bernard-Soulier syndrome, but earlier this year we reported a dominant mode of inheritance resulting in a milder platelet phenotype." (PMID 28669401, 2017). "Bernard-Soulier Syndrome: GP1BA, GP1BB, or GP9 genes cause a disorder of large platelets." (PMID 40822568, 2024). "Bernard-Soulier syndrome (BSS; MIM #231200) is a rare autosomal-recessive bleeding disorder caused by biallelic variants in the GP1BA, GP1BB, and GP9 genes that encode the subunits GPIbα, GPIbβ, and GPIX, respectively, of the GPIb-IX receptor complex." (PMID 34638529, 2021).
bleeding disorder (4 papers, 2013 to 2017). "Bernard–Soulier syndrome (BSS) is an extremely rare (1: 1,000,000) bleeding disorder of platelet adhesion, caused by defects in the glycoprotein genes GP1BA (encoding GPIbα), GP1BB (encoding GPIbβ) and GP9 (GPIX) with autosomal recessive inheritance pattern." (PMID 25275492, 2014).
DiGeorge syndrome (3 papers, 2013 to 2025). "Among them, CRKL, TBX1, TXNRD2, GP1BB were known to be involved in DiGeorge syndrome." (PMID 26742958, 2016). "Gp1bb, a gene located within the DiGeorge syndrome critical region, was upregulated in NKO mutants." (PMID 24131868, 2013). "Gp1bb is a gene located within the DiGeorge syndrome critical region." (PMID 24131868, 2013).
Thrombocytopenia (2 papers, 2010 to 2017). A reduction in the number of circulating thrombocytes. "RUNX1, ANKRD26, MYH9, ACTN1, and GP1BB had ranks of 1, 3, 8, 16, and 74, respectively, with none of the other loci in the top 20 ranks being known to be implicated in thrombocytopenia." (PMID 28669401, 2017). "We speculate that the prolonged interaction of blood platelet expressed GP1BB with HIV might be responsible for thrombocytopenia observed in HIV infection." (PMID 20967291, 2010).
autosomal dominant macrothrombocytopenia (1 paper, 2021). This syndrome is characterized by congenital thrombocytopenia associated with the presence of large platelets. "We subsequently identified the c.528_550del variant in GP1BB in a second pedigree, which was referred for investigation of autosomal-dominant macrothrombocytopenia." (PMID 34638529, 2021). "However, a limited number of variants in the GP1BA or GP1BB genes have been previously associated with mild autosomal-dominant macrothrombocytopenia; of note, most of these variants have been implicated in classical biallelic BSS when present in homozygosis or compound heterozygosis." (PMID 34638529, 2021). "Thus, our results enlarge the spectrum of GP1BB variants associated with autosomal-dominant macrothrombocytopenia without a significant bleeding tendency and suggest a critical role for the cytoplasmic tail of GPIbβ in platelet production." (PMID 34638529, 2021).
cardioembolic stroke (1 paper, 2014). "Another gene involved in the clotting cascade, GP1BB (glycoprotein Ib (platelet), beta polypeptide) was up regulated only in females at 24 h following cardioembolic stroke." (PMID 25036109, 2014).
COVID-19 (1 paper, 2023). A disease caused by infection with severe acute respiratory syndrome coronavirus 2. "Comprising platelet activation, coagulation and wound healing GO terms and platelet-associated genes such as MYL9, ITGB3, GP1BB, TBXA2R and GP6, expression of the Magenta module increased modestly over time and was consistently higher in patients with severe COVID-19." (PMID 37365222, 2023).
osteosarcoma (1 paper, 2020). A usually aggressive malignant bone-forming mesenchymal neoplasm, predominantly affecting adolescents and young adults. "High expression of CYP26B1, GP1BB, and IFI44 in osteosarcoma patients was correlated with good prognosis, while high expression of DDX10 and FOXA2 in osteosarcoma patients was associated with poor prognosis." (PMID 32284759, 2020). "Three of highly expressed genes (DDX10, FOXA2, and HEY1) were correlated with poor prognosis, while three of lowly expressed genes (CYP26B1, GP1BB, and IFI44) showed the opposite trend in patients with osteosarcoma." (PMID 32284759, 2020).
tumor (4 papers, 2008 to 2021). "Downregulation of cell-cell contact to facilitate EMT and tumor mass blood transport is achieved by deletion of epithelial cell adhesion regulatory genes that include GP1BB and PCDHGA11 in our resultant deleted genes list." (PMID 27136531, 2016).
GP1BB also shares sentences with these, for which no sentence is quoted: Macrothrombocytopenia (3 papers); cancer (2); infection (2); malaria (2); platelet disorder (2); Arterial thrombosis (1); asthma (1); atherosclerosis (1); Cognitive impairment (1); Graves disease (1); insulinomas (1); psoriasis (1); systemic lupus erythematosus (1); thrombosis (1); van den Ende-Gupta syndrome (1).